TPSAB1 (tryptase alpha/beta 1)
Description:
Tryptase is the major neutral protease present in mast cells and is secreted upon the coupled activation-degranulation response of this cell type. May play a role in innate immunity. Isoform 2 cleaves large substrates, such as fibronectin, more efficiently than isoform 1, but seems less efficient toward small substrates.
Synonyms: TPS1; TPS2; TPSB1; TPSB2; Tryptase-2
Tractability: Small molecule: a structure with a bound ligand is known; a high-quality ligand is known; it has a high-quality binding pocket; it belongs to a druggable protein family. Antibody: its Gene Ontology location is reachable by antibodies, with high confidence; UniProt places it where antibodies can reach, with medium confidence; UniProt predicts a signal peptide or a membrane-spanning region. PROTAC: a small molecule that binds it is known.
Target class: Serine protease; Enzyme; Serine protease PA clan; Serine protease S1A subfamily; Protease
Gene: Protein-coding gene on chromosome 16 (1,239,266 to 1,242,555, forward strand). Ensembl gene ENSG00000172236.
Subcellular location: Secreted
Subcellular location (Human Protein Atlas): Vesicles; Predicted to be secreted
Pathways (Reactome):
Extracellular matrix organization: Activation of Matrix Metalloproteinases
Gene Ontology:
Molecular function: identical protein binding; protein binding; serine-type endopeptidase activity; serine-type peptidase activity; peptidase activity
Biological process: extracellular matrix disassembly; defense response; proteolysis
Cellular component: extracellular matrix; extracellular region
Genetic constraint (gnomAD): Loss-of-function variants: 13 observed, 9.34 expected, observed/expected ratio (o/e) 1.39, 90% interval 0.89 to 1.9. That is too few expected variants to judge how well the gene tolerates losing a copy. Missense variants: 152 observed, 139.88 expected, observed/expected ratio (o/e) 1.09, 90% interval 0.95 to 1.24. Synonymous variants: 56 observed, 51.12 expected, observed/expected ratio (o/e) 1.1, 90% interval 0.88 to 1.37.
Homologues: Orthologues: chimpanzee TPSB2 (95% identical), mouse Tpsb2 (76% identical), rat Tpsb2 (75% identical), mouse Tpsab1 (74% identical), rat Tpsab1 (74% identical), zebrafish zgc:165423 (40% identical), zebrafish prss60.1 (40% identical), zebrafish prss60.2 (39% identical), Drosophila melanogaster flz (39% identical), zebrafish si:dkey-16l2.17 (39% identical), zebrafish prss60.3 (38% identical), zebrafish zgc:123295 (36% identical), and 49 more. Paralogues in human: TPSB2 (99% identical), TPSD1 (73% identical), TPSG1 (43% identical).
Diseases named in the same sentence as TPSAB1 in open-access papers:
TPSAB1 is named in the same sentence as 42 diseases in open-access papers, as found by Europe PMC text mining. Sharing a sentence is not in itself a finding about the gene and the disease. The quoted sentences say what the papers report.
asthma (5 papers, 2015 to 2025). "We close by highlighting a MOSAIC-specific positively selected sites near the active site of TPSAB1, an enzyme linked to asthma, heart disease, and irritable bowel disease." (PMID 25711833, 2015). "Mast cell TPSAB1 expression is associated with a better clinical response to corticosteroids in individuals with asthma, and corticosteroids have been shown to suppress TPSAB1 expression in bronchial epithelial cells." (PMID 38540988, 2024). "We further used a one-to-one format for comparison and validated with the GSE63142 dataset The genes CEACAM5, PRR4, CPA3, POSTN, TCN1, CST1 (Cystatin-SN), CLCA1, TPSAB1 and NOS2 (Nitric oxide synthase 2) were highly expressed in patients with asthma." (PMID 39963184, 2025). "Direct comparison between the airways within severe asthma identified greater expression of mast cells proteases (CPA3, TPSB2, TPSAB1) in the peripheral airways." (PMID 28045928, 2017).
mastocytosis (4 papers, 2021 to 2025). A clonal myeloproliferative neoplasm characterized by the proliferation and accumulation of neoplastic mast cells in one or multiple organs or organ systems. "Hereditary α-tryptasemia (HαT)—a genetic trait caused by increased α-tryptase-encoding typtase alpha/beta-1 (TPSAB1) copy number—is associated with adult mastocytosis." (PMID 40649802, 2025). "This pronounced difference indicates a possible pathogenic role of TPSAB1 copy number gains in the evolution of mastocytosis." (PMID 33799959, 2021). "Although development of a KIT mutation is not directly related to the increased number of copies of the TPSAB1 gene, the high prevalence of HαT in mastocytosis hints at a potential pathogenic role of germline α-tryptase-encoding TPSAB1 copy number gains in disease development." (PMID 40649802, 2025). "The authors assumed the possibility of a pre-disease phase, and indicated a relationship of increased TPSAB1 copy numbers and gene–dosage in the development and clinical manifestations of clonal MC diseases, such as mastocytosis." (PMID 33671092, 2021). "The results from our study support that elevated BST levels in the absence of evidence of mastocytosis are in most cases associated with an increased TPSAB1 copy number." (PMID 39600380, 2024). "In patients with elevated BST but no mastocytosis, the most likely cause of elevated BST was an increase in the copy number of the TPSAB1 gene." (PMID 39600380, 2024).
basal cell carcinoma (3 papers, 2022 to 2025). A carcinoma involving the basal cells. "Additionally, a decrease in the expression of tryptase (TPSAB1) and chymase (CMA1) genes has been reported in MC compared to normal skin and basal cell carcinoma." (PMID 41373472, 2025).
anaphylaxis (2 papers, 2021 to 2025). An acute hypersensitivity reaction that occurs from exposure to an allergen. "The rs765144578 variant in TPSAB1 remained significantly associated with cefaclor‐induced anaphylaxis, reaching genome‐wide significance (p < 1 × 10−8)." (PMID 40974473, 2025). "A rare missense variant, rs765144578 in TPSAB1 was strongly associated with anaphylaxis and remained significant in the validation control group." (PMID 40974473, 2025). "Association between the rs765144578 variant in TPSAB1 and hypotension in patients with cefaclor‐induced anaphylaxis." (PMID 40974473, 2025). "Subgroup analysis revealed a strong association between the rs765144578 variant in TPSAB1 and hypotension as a manifestation of anaphylaxis." (PMID 40974473, 2025). "Notably, rs765144578 variant in the TPSAB1 locus demonstrated the strongest association with cefaclor‐induced anaphylaxis (adjusted p < 0.001; risk allele frequency [RAF] 0.44 vs. 0.05; odds ratio [OR] 98.96; 95% confidence interval [CI], 17.65–555.04)." (PMID 40974473, 2025). "Genetic variants in TPSAB1 and HLA‐DRB5 may contribute to the risk of cefaclor‐induced anaphylaxis, and TPSAB1 may also be associated with severity." (PMID 40974473, 2025). "In contrast, the HLA‐DRB5 and the TPSAB1 are more plausibly implicated in drug induced anaphylaxis." (PMID 40974473, 2025). "Therefore, TPSAB1 genotyping should be included in the diagnostic algorithm in patients with symptomatic SM, severe anaphylaxis or MCAS." (PMID 33671092, 2021). "Furthermore, the co‐occurrence of rs765144578 variant in TPSAB1 and rs192498095 variant in HLA‐DRB5 demonstrated a markedly stronger association with anaphylaxis than either variant alone." (PMID 40974473, 2025). "Taken together, TPSAB1 and HLA‐DRB5 emerge as meaningful genetic contributors to cefaclor‐induced anaphylaxis based on both biological plausibility and case–control association signals." (PMID 40974473, 2025).
psoriasis (2 papers, 2016 to 2021). An autoimmune condition characterized by red, well-delineated plaques with silvery scales that are usually on the extensor surfaces and scalp. "However, it is interesting to note that altered expression of genes including Tpsab1, Shh, S100a7a and Il20, which are associated with tumorigenesis or psoriasis, was observed in the microarray analysis." (PMID 27756876, 2016). "As a result, we found that the mRNA expression level of KIT, ENPP3, CMA1, CTSG, TPSAB1 and TPSG1 is decreased in PP compared with PN and NN, indicating the fraction of total mast cells is decreased in psoriasis." (PMID 34887864, 2021).
rosacea (2 papers, 2020 to 2023). A chronic erythematous skin disorder that affects the face. "Moreover, EGCG also reduced the expressions of the neutrophil-attracting chemokines (Cxcl15 and Cxcl1), macrophage markers (Cd68 and Itgam), and mast cell-related genes (Tpsab1 and Cma1) in LL-37-induced rosacea-like lesions." (PMID 36937834, 2023).
ascariasis (1 paper, 2024). An infection that is caused by the roundworm Ascaris lumbricoides, many cases of which remain asymptomatic. "Our finding of an increase of TPSAB1 has also been reported in eosinophilic chronic obstructive pulmonary disease, suggesting that an interaction between ILC2, mast cells and eosinophilic inflammation could be present in ascariasis." (PMID 39524451, 2024).
Cachexia (1 paper, 2023). Severe weight loss, wasting of muscle, loss of appetite, and general debility related to a chronic disease. "In a study involving mice with moderate and severe cachexia, there was a significant difference in the tryptase alpha/beta 1 (TPSAB1) and CD68 genes from the innate immune system compared to healthy mice, serving as a control group." (PMID 37629547, 2023).
chronic pancreatitis (1 paper, 2011). A chronic inflammatory process causing damage and fibrosis of the pancreatic parenchyma. "It is also important to note that while most of the digestive enzymes were down-regulated in severe chronic pancreatitis and pancreatic adenocarconoma, tryptase (TPSAB1) was up-regaulated in chronic pancreatitis and adenocarinoma." (PMID 22132114, 2011).
COVID-19 (1 paper, 2021). A disease caused by infection with severe acute respiratory syndrome coronavirus 2. "Consistent with the serum findings from SARS-CoV-2 patients, the MC protease genes TPSB2 and TPSAB1 which encode for α- and β-tryptase, respectively, were significantly elevated in lungs from COVID-19 patients, suggesting increased activation of lung MCs in COVID-19 inflammation." (PMID 33777047, 2021).
emphysema (1 paper, 2021). "For females the top differential emphysema-restricted genes are the mast cell specific genes TPSB2, TPSAB1 and CPA3." (PMID 34145303, 2021).
endometriosis (1 paper, 2023). The growth of functional endometrial tissue in anatomic sites outside the uterine body. "Moreover, the mRNA levels of C-KIT and TPSAB1 were higher in patients with endometriosis-related pain than those without it." (PMID 36845134, 2023).
itch (1 paper, 2022). "Pruritogens, including TAC1, IL-2, IL-31, TPSAB1, TPSB2, and TPSG1, and the key enzymes that are attributed to itch, including HDC and TPH1, were detected by RNA-seq." (PMID 35632808, 2022).
lung carcinoma (1 paper, 2025). "It has been demonstrated previously that the other hub mRNAs (PBX1, PLIN2, and TPSAB1) are closely related to the progression of lung cancer and COPD by regulating the cell cycle and cell proliferation." (PMID 39940682, 2025).
Sotos syndrome (1 paper, 2024). Sotos syndrome is a rare multisystemic genetic disorder characterized by a typical facial appearance, overgrowth of the body in early life with macrocephaly, and mild to severe intellectual disability. "These sSVs explain otherwise cryptic variation in medically relevant regions such as the TPSAB1 gene, 8p23.1, 22q11 and Sotos syndrome regions." (PMID 39266513, 2024).
urticaria (1 paper, 2023). A vascular reaction of the skin characterized by erythema and wheal formation due to localized increase of vascular permeability. "We found significant trans-pQTL associations of the GCSAML urticaria-associated variant with plasma levels of five proteins encoded by TPSAB1, TPSB2, KIT, SELP, and SIGLEC6 (P-values < 1.0 × 10−7)." (PMID 37430141, 2023). "The urticaria-associated variant rs4410077[T] at TPSD1, does not correlate with a reported copy number of TPSAB1 (r2 = 0.011)." (PMID 37430141, 2023).
tumor (17 papers, 2015 to 2026). "We found mast cells, which were characterized by specific expression of TPSAB1, potentially enriched in the tumor core, consistent with previous reports." (PMID 36423636, 2022). "Tumor immune cells (PTPRC/CD45+) also consisted of B cells (MS4A1/CD20+), plasma cells (XBP1+), macrophages (CD14+), dendritic cells (CD80+, CD86+), and mast cells (TPSAB1+)." (PMID 35742914, 2022). "TPSAB1 (Tryptase), is a major mast cell secretory protease, which has been shown to cleave, activate, or degrade ECM components and mediate ECM remodeling within the tumor microenvironment." (PMID 33799802, 2021). "In addition, a significantly high expression of the gene set of mast cell proteinase CPA3, TPSAB1, and TPSB2 was also noted in the tumor adjacent lungs (Tukey HSD test: p < 2.0 × 10−7 for each pair of comparisons)." (PMID 29483918, 2018). "Reclustering revealed 11 distinct subclusters, of which nine were enriched in tumor and interface zones and designated as plasma B cells (clusters 2 and 10, IGHG1 +), follicular B cells (clusters 0, 3, 6, 8 and 9, MS4A1 +), immature B cells (cluster 7, IL7R +) and mast cells (cluster 5, TPSAB1 +)." (PMID 37644609, 2023).
adenocarcinoma (1 paper, 2020). A common cancer characterized by the presence of malignant glandular cells. "In adenocarcinoma, high TPSAB1 expression in immune cells correlated with reduced malignant cell expression of proliferation and cell cycle genes as well as of genes related to metastasis." (PMID 32381040, 2020). "We noted that TPSAB1 (Tryptase Alpha/Beta 1) was highly expressed in sorted immune cells from both adenocarcinoma and SCC (p < 2.2 × 10− 16 by ANOVA) and is favorably prognostic in both histologies across multiple datasets in PRECOG." (PMID 32381040, 2020).
TPSAB1 also shares sentences with these, for which no sentence is quoted: infection (11 papers); cancer (5); allergic disease (2); glioma (2); melanoma (2); allergic asthma (1); allergic rhinitis (1); Allergy (1); autonomic dysfunction (1); connective tissue abnormalities (1); Cushing syndrome (1); fungal infection (1); gastrointestinal disorders (1); genetic disorder (1); heart disease (1); hepatocellular carcinoma (1); Hyperglycemia (1); Hypoglycemia (1); myeloid neoplasm (1); non-alcoholic fatty liver disease (1); non-small cell lung carcinoma (1); pericarditis (1); renal carcinoma (1); small cell lung carcinoma (1).